IL10 (interleukin 10)
Diseases named in the same sentence as IL10 in open-access papers (continued):
Sharing a sentence is not in itself a finding about the gene and the disease.
malaria (continued). "Collectively, these data show that early, Plasmodium-induced type I IFNs promote the development of effector Tr1 responses and Tr1 co-expression of IL-10 and IFN-γ during experimental malaria." (PMID 27732671, 2016). "Furthermore, IFN-γ/IL-10 ratio has been reported to increase proportionally to malaria clinical severity, and it is possible that cases of malaria and dengue co-infection presenting with lower levels of IL-10 and higher levels of IFN-γ may be reflected in an increased disease severity." (PMID 26271921, 2015). "The high plasma level of IL-10 in eBL, and the high frequency of CD4+CD25hi+ Treg cells in malaria and eBL, give credence to the parallel between dysregulation of the immune system in the two diseases." (PMID 28536409, 2015). "The means levels of IFN-γ (66.71 pg/mL [2.00-3629.00]) and IL-10 (795.34 pg/mL [1.15-16782.93]), were higher in plasma of malaria (+) when compared with malaria (−) group (IFN-γ 19.44 pg/mL [1.46-3919.00] and IL-10 1.29 pg/mL [0.40-989.00])." (PMID 25627396, 2015). "Together, these findings suggest that a heterologous T helper memory cell population is critical to the malaria immune response because it maintains both cellular and humoral immunity through IFN-γ, IL-21, and CXCR5, and regulates pathology via IL-10." (PMID 26646149, 2015). "In human malaria, a link between enhanced IFN-γ, TNF, IL-6, IL-10 and nitric oxide (NO) levels and severity of the disease have long been reported, although this is not a consistent finding." (PMID 25627396, 2015). "In contrast, Il10, a marker of regulatory macrophages, was expressed more highly in the CD11b+ liver cell fraction of mice infected with P. yoelii or co-infected with P. yoelii and S. Typhimurium, suggesting that malaria may polarize liver macrophages to a M2-like regulatory phenotype." (PMID 24787713, 2014). "Previous studies using recombinant proteins or peptides based on PfEMP1 expressed on laboratory lines showed that individuals living in malaria-endemic areas harbored both IFN-γ− and IL-10–secreting Ag-specific CD4+ T cells." (PMID 24453249, 2014). "Our results suggest that the functional phenotype of the malaria-specific T cell response was heavily influenced by prior malaria exposure intensity, with CD4+ T cells co-producing IFNγ and IL10 dominating this response among highly exposed children." (PMID 24415936, 2014). "In the context of murine malaria models, CD4 T cells were shown to be an important cellular source of immunomodulatory IL-10." (PMID 24787713, 2014). "Here we show that P. falciparum-inducible IL-10 and TGF-β production/expression is upregulated after the resolution of febrile malaria relative to that which is inducible at the healthy baseline of the same individuals." (PMID 24743880, 2014). "Previous studies on the impact of cytokines on clinical outcome in malaria have identified TNF, IFN-γ, IL-1β, IL-6, IL-10, IL-12, transforming growth factor β and IP-10 as important mediators, but data on IL-8in this setting are more limited." (PMID 25503583, 2014). "Clinical malaria cases exhibited an immunological profile qualitatively similar to that of the VL patients, with increased concentrations of TNF, IL-6 and IL-10 (P <0.0001) and, to a less extent, IFN-γ and IL-17A (P <0.01), IL-4 and IL-12p70 (P <0.05)." (PMID 24886212, 2014). "Taken together these data point toward a protective effect of P. falciparum-specific IL-10 producing Th1 cells in malaria, a hypothesis supported by a cross-sectional study in The Gambia which showed a higher frequency of total IL-10 producing Th1 cells in children with mild versus severe malaria." (PMID 24743880, 2014). "Circulating levels of interferon (IFN)-γ, interleukin (IL)-2, IL-4, IL-6, IL-10, IL-12p70, IL-13, IL-17A and tumor necrosis factor (TNF) were assessed in sera of patients infected with active VL and/or malaria and healthy individuals from Gedarif State, Sudan." (PMID 24886212, 2014).
malaria (continued). "However, these IFNγ/IL-10 co-producing cells were not independently associated with protection from future malaria, and may be associated with increased risk." (PMID 24415936, 2014). "In both malaria and coinfected groups the median levels of TNF-α, IL-2, IL-10, IL1-β, MCP-1, and IL-6 were observed to be mostly significantly increased compared with those intestinal parasites and uninfected groups (P < 0.001 for all comparisons)." (PMID 25309052, 2014). "Similar to IL-10 producing CD4+ T cells, plasma IL-10 strongly correlated with recent malaria (Spearman's Rho = 0.30, P = 0.009)." (PMID 24415936, 2014). "In humans, IL-10 and TGF-β levels increase in serum during acute febrile malaria and then fall after treatment, consistent with a role for these cytokines in restraining and resolving P. falciparum-induced inflammation during a single malaria episode." (PMID 24743880, 2014). "Plasma endotoxin levels in severe malaria negatively correlated with IL6, IL10 and TGFβ (Spearman rho: TNFα: r= −0.122, p=0.121; IL6: r=−0.330, p<0.0001; IL10: r=−0.461, p<0.0001; TGFβ: r=−0.173, p<0.027)." (PMID 23497104, 2013). "T-cell sub-populations (CD4, CD3 and γδTCR) were intracellularly stained for IL-10, IFN-γ and TNF following polyclonal stimulation or stimulated with malaria parasites." (PMID 23294670, 2013). "IL-10(+)CD19(+) B cells and IL-10(+)CD3(+) T cells in infected spleen were significantly increased in number after being exposed to malaria three times compared to infected 0-cure controls." (PMID 23724100, 2013). "It has been suggested that a reliable predictor of malaria severity is comparison of the ratio between TNF and IL-10 protein levels in the plasma." (PMID 23874969, 2013). "Of note, in all subgroups of children with severe malaria plasma concentrations of IL6, IL10 and TGFβ were reduced in the presence of endotoxaemia compared to those without endotoxaemia." (PMID 23497104, 2013). "In fact, in the present study, high plasmatic levels of IL-10 and low plasmatic levels of TNF were observed in malaria patients." (PMID 24041406, 2013). "Furthermore, an analysis of IL10 single nucleotide polymorphisms (SNPs) in Gambian children found a common haplotype that was strongly associated with protection against severe malaria by case-control analysis but not by Transmission Disequilibrum Test (TDT) analysis of the same population." (PMID 24312262, 2013). "After evaluating the cytokine profile (IL-2, IL-4, IL-6, IL-10, TNF-α, IFN-γ and IL-17) in the patients’ sera, levels of IL-6, IL-10 and IFN-γ were elevated in malaria patients compared to HV." (PMID 23723981, 2013). "Immigrants and travelers with malaria had higher levels of IFN-γ, IL-6, and IL-10 (P<0.0100) than patients with other diseases, and IL-8 and IL-1β were elevated in immigrants with malaria (P<0.0500)." (PMID 23967342, 2013). "In our study, the role of IL-10 derived from CD19(+) cells, malaria specific antibodies and the mechanism how the donor CD19(+) cells interact with other cells in the recipient that develops primary malaria infection have not been confirmed." (PMID 23724100, 2013). "The cytokine balance seems to influence malaria outcome, with TNF, IFN-γ and IL-10 emerging as key players in both experimental models and in human observational studies." (PMID 23433077, 2013). "IL-10 and TNF responses to a T cell stimulus were higher in AC than in any of the three clinical malaria groups, suggesting an impaired T cell responsiveness in malaria (regardless of the clinical presentation) as observed by others." (PMID 22853732, 2012). "We found significantly elevated protein concentrations of IL-10, monocyte chemoattractant protein-1 (MCP-1), IFN-γ, TNF-α and IL-6 in lungs, spleens, livers as well as sera of malaria-tuberculosis co-infected mice." (PMID 23110184, 2012).
malaria (continued). "Similar observations have been reported where malaria patients responded to P. falciparum infected erythrocytes with significant increases in the percentage of IL-2, IFN-γ, and TNF, but also IL-10, positive cells." (PMID 22280502, 2012). "There is less field data available on the relevance of individual cytokines in naturally acquired immunity to malaria, e.g. IL-12, IFN-γ, TNF, or IL-10." (PMID 22280502, 2012). "It has also been suggested that anti-inflammatory Th2-type cytokines (IL-4, IL-10, and TGF-beta) downregulate Th1-type cytokines and the proinflammatory response, thereby preventing subjects from severe forms of malaria." (PMID 23316245, 2012). "UA levels also correlated with IL-6, IL-10, sTNFRII, MCP-1, IL-8, TNFα and IP-10 levels, all of which were elevated in children with severe malaria." (PMID 23071567, 2012). "In the patients group who had been exposed to only one malaria episode, IFN-γ and IL-10 levels were higher than in patients who had had at least one previous episode." (PMID 21917128, 2011). "Comparing asymptomatic individuals and cases described as severe malaria, a study performed in Brazil showed that the IFN-γ:IL-10 ratio was higher in severe cases, while IL-10 levels were elevated in asymptomatic individuals." (PMID 21917128, 2011). "As part of the inflammatory cascade, IL-10 is thought to have a suppressive effect on tumor necrosis factor-α (TNF-α), resulting in diminished malaria disease severity." (PMID 21447146, 2011). "IL-12p70, IL-10, and sTNF-RII are strongly correlated with the Pfs-IgG3 malaria exposure marker, and levels of IL-10 and sTNF-RII are significantly greater in children who are co-infected with P. falciparum and S. mansoni." (PMID 21912707, 2011). "Thymus (CD4+, and CD25+ T cells) were the major cellular source of IL-10 and TGF-b1 cytokines in malaria infected red blood cells (iRBC) when co-cultured with PBMCs." (PMID 21439091, 2011). "Concentrations were highly variable in the malaria patients, ranging from 0.0 to 332.85 pg/ml for IFN-γ, and from 0.0 to 586.33 pg/ml in IL-10." (PMID 21917128, 2011). "In the acute uncomplicated malaria, it has been demonstrated that peripheral blood CD4+ T cells producing both IFN-γ and IL-10 were significantly increased during drug-induced clearance of parasitaemia." (PMID 20856680, 2010). "Schistosoma haematobium infection was shown to reduce malaria severity by increasing Th2 responses in P. falciparum-infected children; a recent ex-vivo study indicates that helminth infections cause an increase in IL-10 but no change in TNF, indicating suppression of pro-inflammatory responses." (PMID 20051114, 2010). "Malaria-naïve adults experimentally infected with Pf had increased expression of TNF-α, IL-1β and IL-6 in response to a TLR4 ligand (LPS) and IL-6 and IL-10 in response to TLR2 + TLR1 ligand (Pam3Cys) on day 8 of the infection." (PMID 19691558, 2009). "In this study we investigated the role of commonly accepted factors for Foxp3 induction, TCR stimulation and cytokines such as IL-2, TGFβ and IL-10, in the generation of human CD4+CD25+Foxp3+ T cells by the malaria parasite Plasmodium falciparum." (PMID 19680449, 2009). "Malaria-infected women had significantly elevated IL-10 levels and a decreased IL-6:IL-10 ratio compared with non-infected women (p = 0.005)." (PMID 41666219, 2026). "NK cells from malaria-naive individuals incubated in IL-15 alone for 6 days were used as a negative control for IL-10 production." (PMID 40337867, 2025). "IL-10 production was not different in NK cells sampled from individuals prior to, during, or after malaria in either cytolytic assay." (PMID 40337867, 2025). "The high levels of IL-10 responses in children with acute malaria and significant suppression of IFN-γ–secreting cells witnessed following antigenic stimulation are further indicative of the dysregulation of the immune response induced by malaria." (PMID 41285032, 2025).
malaria (continued). "Systemic cytokines are detected in both nonsevere and severe malaria, and the ratio of IL-10 levels to inflammatory cytokines can be an indicator of disease." (PMID 40337867, 2025). "Evidence of malaria-induced immunosuppression was observed in our data in cytokine secretory profiles, where CD4 and CD8 T-cell responses were dominated by upregulation of IL-10 and downregulation of IFN-γ–secreting cells." (PMID 41285032, 2025). "Here, we showed that NK cells from participants with malaria experience make significantly more IL-10 than participants with no malaria experience." (PMID 40337867, 2025). "Our findings suggest that clinical malaria did not result in the impairment of T-cell activation, but rather induced shifts in cytokine secretion in favor of IL-10." (PMID 41285032, 2025). "Therefore, many studies are conducted on rodent malaria to examine resistance, drug screening, and inflammatory cytokines like TNF-α, IFN-γ, and IL-10." (PMID 39204168, 2024). "Regrettably, we could neither have a follow up of the few patients with elevated IL-10 serum levels in the convalescent phase nor ascertain the possible presence of polymorphisms associated with lower IL-10 circulating levels as reported in individuals infected with malaria." (PMID 39194742, 2024). "In addition, malaria status predicted TNF‐α, IFN‐ɣ, IL‐1β, IL‐6, GM‐CSF and IL‐10 levels, whiles anemia severity predicted only IL‐3, IL‐10 and TGF‐β levels." (PMID 39240033, 2024). "Malaria and dengue coinfections showed a significant increase in proinflammatory cytokines such as IFN-γ, IL-1, IL-6, and IL-12; Th2 cytokines such as IL-4; anti-inflammatory cytokines such as IL-10 and IL-13; and Th17 cytokines such as IL-17." (PMID 36716305, 2023). "The subgroup analysis also showed a higher SMD of the IL-10 level in patients with severe P. knowlesi malaria than in those with non-severe P. knowlesi malaria (p < 0.001, pooled SMD: 2.36, 95% CI: 1.79–2.94, I2: 44.06%, two studies)." (PMID 36668942, 2023). "An analysis of the cord blood revealed that TNF, IL-1β, and IL-5 were associated with severe malaria but IL-4, IL-6, IFN-γ, and IL-10 did not relate to severe malaria." (PMID 36668942, 2023). "The difference in the IL-10 levels between patients with severe malaria and those with non-severe malaria was estimated using data from 19 studies." (PMID 36668942, 2023). "While IL-10 producing CD4 T cells have been well recognised in malaria, this study identifies B cells as a major source of IL-10 during human malaria." (PMID 37968278, 2023). "The production of the antiinflammatory cytokine IL-10 and expression of coinhibitory receptors by parasite-specific CD4+ T cells are important components of the immune regulatory networks that arise during malaria." (PMID 37781920, 2023). "Increased IL-6 and IL-10 levels were observed in cerebral malaria compared with severe malaria without a cerebral involvement." (PMID 36668942, 2023). "After the publication bias was adjusted by the trim and fill method, the pooled SMD in the IL-10 levels between severe and non-severe malaria was 0.743 95% CI: 0.085–1.401)." (PMID 36668942, 2023). "The results showed that patients with severe malaria had a higher IL-10 level than those with non-severe malaria (p = 0.03, pooled standardized mean difference: 0.74, 95% CI: 0.08–1.40, I2: 97.22%, 19 studies/21 sub studies)." (PMID 36668942, 2023). "The inflammatory condition of malaria is characterized by free radical generation and excessive release of pro-inflammatory cytokines such as tumor necrosis factor (TNF)-alpha, interleukin (IL)-12, IL-10, IL-6, and interferon (IFN)-gamma." (PMID 36852070, 2023). "However, multiple lines of evidence have shown that malaria drives the expansion of regulatory CD4 T cells, particularly Type 1 regulatory (Tr1) cells that co-produce IFNγ and IL-10 in this disease." (PMID 37968278, 2023).
malaria (continued). "Increased TNF, IFN-γ, IL-1, IL-2, IL-6, IL-10, TGF-β, CCL2, CCL3, and G-CSF levels and decreased IL-5, IL-12, IL-17, and CCL11 levels were observed in malaria monoinfection compared to intestinal parasite monoinfection." (PMID 36716305, 2023). "The present meta-analysis results demonstrated that patients with severe malaria had a higher mean IL-10 level than those with non-severe malaria." (PMID 36668942, 2023). "The funnel plot demonstrated the asymmetrical distribution of the SMDs in the IL-10 between severe and non-severe malaria from the middle line (pooled SMD)." (PMID 36668942, 2023). "When stratified by malaria sero-status, IL-1α (p=0.034), IL-5 (p=0.023) and IL-10 (p=0.024) were significantly higher in malaria sero-positive than sero-negative volunteers." (PMID 38274822, 2023). "Similarly, within B cell subsets, malaria drove a significant increase in HIF1A expression, which has previously been shown to be a critical transcription factor for the induction of IL-10 producing Bregs in mouse models." (PMID 37968278, 2023). "In addition, significant decreases in IL-10 and CXCL5 levels were observed in coinfections compared to malaria monoinfections." (PMID 36716305, 2023). "The meta-analysis results demonstrated increased IL-10 levels in patients with severe malaria compared with those with non-severe malaria." (PMID 36668942, 2023). "Overall, the meta-analysis results showed that patients with severe malaria had a higher SMD of the IL-10 levels than those with non-severe malaria (p = 0.03, pooled SMD: 0.74, 95% CI: 0.08–1.40, I2: 97.22%, 19 studies/21 sub-studies)." (PMID 36668942, 2023). "In contrast, multigravid women had higher percentages of CD4+ T cells that produced TNFα in the absence of IFNγ and IL-10, and these cells were correlated with protection against malaria in pregnancy." (PMID 37634385, 2023). "The meta-analysis results demonstrated that patients with severe malaria have increased IL-10 levels compared to those with non-severe malaria." (PMID 36668942, 2023). "Hence, these results show that CD4+ T cell–intrinsic type I IFN signaling is required for optimal IL-10 and IFN-γ production as well as Tr1 cell development in vivo in experimental malaria." (PMID 37781920, 2023). "In fact, IL-10– and IFN-γ–coproducing CD4+ T (type I regulatory [Tr1]) cells comprise a substantial fraction of cells responding to parasite antigen stimulation of immune cells from African children living in malaria-endemic areas." (PMID 37781920, 2023). "In this study, a comparable IL-10 competent B-10 cell subset (regulatory B cells) was characterized during lethal and non-lethal infection with malaria parasites using the mouse model." (PMID 35625397, 2022). "In our analysis, IL-10 was also increased in patients with mild malaria but, unlike TGF-β and IL-9, its concentration was also significantly higher in severe cases than in controls." (PMID 36293524, 2022). "Elevated levels of IL-4 and IL-10 and reduced levels of IL-6 were detected in the malaria positive samples in comparison to the negative ones in the three types of the samples investigated." (PMID 33422078, 2021). "For example, CD8+ T-cell exhaustion can be characterized by a number of cell surface markers including PD-1, Tim-3, LAG-3, and IL-10 plasma levels, and earlier studies already identified that PD-1 dependent exhaustion of CD8+ T cells in malaria facilitated a chronic disease state." (PMID 34485170, 2021). "In this report, we explored these key knowledge gaps by genetically and biochemically manipulating IL-10 and IL-10 signaling during a non-lethal Plasmodium yoelii murine model of malaria." (PMID 33529242, 2021). "The development of liver disease in IM pregnant WT mice infected with P. berghei NK65 suggested that the development of liver disease during malaria in pregnancy was not suppressed by IL-10." (PMID 34906158, 2021).